CEBPZOS (CEBPZ opposite strand)
Synonyms: CEBPZ-AS1
Tractability: Antibody: UniProt predicts a signal peptide or a membrane-spanning region. PROTAC: ubiquitination databases record sites on it; its protein half-life has been measured.
Gene: Protein-coding gene on chromosome 2 (37,191,473 to 37,216,555, forward strand). Ensembl gene ENSG00000218739.
Subcellular location: Mitochondrion membrane
Subcellular location (Human Protein Atlas): Nucleoplasm
Gene Ontology:
Cellular component: mitochondrial membrane; mitochondrion
Homologues: Orthologues: chimpanzee CEBPZOS (99% identical), macaque CEBPZOS (96% identical), pig CEBPZOS (88% identical), rat Cebpzos (82% identical), guinea pig CEBPZOS (80% identical), mouse Cebpzos (79% identical), tropical clawed frog cebpzos (56% identical).
Diseases named in the same sentence as CEBPZOS in open-access papers:
CEBPZOS is named in the same sentence as 3 diseases in open-access papers, as found by Europe PMC text mining. Sharing a sentence is not in itself a finding about the gene and the disease. The quoted sentences say what the papers report.
liver cancer (2 papers, 2022). An epithelial or non-epithelial malignant neoplasm that arises from the liver. "Studies have suggested that CEBPZOS is a prognostic marker of liver cancer related to energy metabolism." (PMID 37305349, 2022). "The role of CEBPZOS as a mitochondrial protein may also affect the energy metabolism of tumor cells in liver cancer, and thereby affect tumor development as well." (PMID 35602603, 2022). "Furthermore, 1000 lasso analysis also identified five genes: ADH4, AKR1B10, CEBPZOS, ENO1, and FOXN2, as the most stable prognosis-related genes associated with energy metabolism in liver cancer." (PMID 35602603, 2022). "Based on the marker genes of this cluster and TCGA database data, the five most stable key genes (ADH4, AKR1B10, CEBPZOS, ENO1, and FOXN2) were identified as energy metabolism-related genes in liver cancer." (PMID 35602603, 2022).
hepatocellular carcinoma (1 paper, 2024). A malignant tumor that arises from hepatocytes. "In a hepatocellular carcinoma (HCC) study, researchers demonstrated that CSPG4P12, combining 5 other genes (BX537318.1, TMEM147, AC015908.3, CEBPZOS, and SRD5A3), served as the signature for prognostic evaluation of HCC." (PMID 38877481, 2024).
CEBPZOS also shares sentences with these, for which no sentence is quoted: tumor (2 papers).